HDAC6 (histone deacetylase 6)
Diseases named in the same sentence as HDAC6 in open-access papers (continued):
Sharing a sentence is not in itself a finding about the gene and the disease.
Retinopathy (2 papers, 2022 to 2024). "For example, apoptosis signal-regulating kinase 1 (ASK1) phosphorylates histone deacetylase 6 (HDAC6) and inhibits the ubiquitin−mediated proteolysis of HDAC6, which contributes to the pathology induced by oxygen changes, suggesting a potential target for the treatment of retinopathy of prematurity." (PMID 39679197, 2024).
blood cancers (1 paper, 2021). "Citarinostat (ACY-241) is a second-generation, bioavailable, and selective inhibitor of class IIb histone deacetylase 6 (HDAC6) that is active against MM and acts synergistically in combination with other therapeutic agents against solid tumors and blood cancers." (PMID 33807514, 2021).
myopathy (1 paper, 2013). A disease of the muscle in which the muscle fibers do not function properly. "VCP was increased by 139.7%, HDAC6 by 98.6%, p62 by 124.8% and NBR1 by 149.2% (P<0.05) in GNE myopathy patients." (PMID 23472144, 2013).
neurodevelopmental disorder (1 paper, 2024). A behavioral and cognitive disorder with onset during the developmental period that involves impaired or aberrant development of intellectual, motor, or social functions. "To date, three neurodevelopmental disorders caused by mutations in genes encoding for HDACs (HDAC4, HDAC6 and HDAC8) and thus belonging to the group of chromatinopathies, have been described." (PMID 38753158, 2024).
psychiatric disorder (1 paper, 2023). A disorder characterized by behavioral and/or psychological abnormalities, often accompanied by physical symptoms. "Experimental data point toward the therapeutic use of HDAC6-selective inhibitors (HDAC6is) for use in both neurological and psychiatric disorders." (PMID 36902164, 2023).
skeletal dysplasia (1 paper, 2024). Any Mendelian diseases that affects growth and development of the skeleton. "HDAC6 has been shown to interact with Runx2, a transcription factor involved in osteoblast differentiation, and other HDACs exhibit high expression patterns in prehypertrophic chondrocytes, indicating their role in endochondral ossification and skeletal dysplasias." (PMID 38439105, 2024).
urological disorders (1 paper, 2016). "Cumulatively, these changes may negate any inhibitory effects that the lack of HDAC6 has on UPEC entry into individual host cells, and suggest roles for HDAC6 in other urological disorders such as urinary retention." (PMID 26907353, 2016).
HDAC6 also shares sentences with these, for which no sentence is quoted: Ewing sarcoma (3 papers); heart disease (3); lung disease (3); multiple sclerosis (3); non-Hodgkin lymphoma (3); retinal diseases (3); uveal melanoma (3); airway hyperresponsiveness (2); autism (2); brain disorder (2); brain injury (2); choroid plexus carcinoma (2); follicular lymphoma (2); Hydrocephalus (2); inflammatory bowel disease (2); intracerebral hemorrhage (2); Peripheral T-cell Lymphoma (2); squamous cell carcinoma (2); steatosis (2); T-cell acute lymphoblastic leukemia (2); T-Cell Lymphoma (2); Ureteral obstruction (2); acute lung injury (1); alcohol use disorder (1); Alexander disease (1); Allergy (1); anal carcinoma (1); angioimmunoblastic T-cell lymphoma (1); Aortic dissection (1); aortic stenosis (1).
A further 77 diseases each share a sentence with HDAC6 in 1 paper.